SOCS3 (suppressor of cytokine signaling 3)
Diseases named in the same sentence as SOCS3 in open-access papers (continued):
Sharing a sentence is not in itself a finding about the gene and the disease.
Sepsis (30 papers, 2007 to 2025). Sepsis is defined as life-threatening organ dysfunction caused by a dysregulated host response to infection. "Studies have shown that SOCS3 expression exerts a protective effect on endothelial cells during sepsis, and its deficiency leads to endothelial dysfunction, thereby exacerbating tissue injury." (PMID 40808951, 2025). "We performed targeted screening of the diagnostic gene SOCS3 to develop a novel therapeutic approach for reducing organ damage in sepsis." (PMID 41306613, 2025). "Single-cell sequencing of pneumonia, sepsis, and sepsis with ARDS found that the monocyte cluster in patients with early ARDS caused by sepsis was characterized by down-regulation of SOCS3 expression and up-regulation of multiple type I IFN-induced genes." (PMID 38035100, 2023). "Notably, the authors showed that mice with SOCS3-deficient macrophages experienced exacerbated Lipopolysaccharide (LPS)-induced sepsis, which was associated with enhanced JAK/STAT pathway activation and increased plasma levels of cytokines/chemokines such as CCL4." (PMID 40586774, 2025). "Research has shown that ADAR1 targets miR-30a to regulate SOCS3 expression, thereby reducing IL-6 levels, mitigating inflammation and organ damage and providing protection against sepsis." (PMID 41306613, 2025). "Five genes were identified as diagnostic biomarkers for sepsis-induced ARDS and cardiomyopathy, with SOCS3 serving as a key hub gene and potential therapeutic target." (PMID 41306613, 2025). "first demonstrated that SOCS3 is upregulated and exhibits time-dependent expression in a mouse model of sepsis." (PMID 40808951, 2025). "The results showed that p‐STAT1, SOCS1 and SOCS3 expression levels decreased after sepsis‐induced intestinal injury compared to the control group." (PMID 39844345, 2025). "To examine the temporal characteristics of SOCS3 expression in patients with sepsis, we analyzed the GSE131411 dataset obtained from the GEO database." (PMID 40808951, 2025). "By comparing transcriptomic changes in whole blood from patients with septic shock and cardiogenic shock, we observed that SOCS3 expression was significantly upregulated in the early stages of sepsis." (PMID 40808951, 2025). "Overall, our findings highlight dexamethasone, resveratrol and curcumin as promising SOCS3-targeting agents for treating sepsis-induced lung injury and cardiomyopathy, paving the way for further in vitro, in vivo and clinical development." (PMID 41306613, 2025). "Using qPCR, we further validated SOCS3 expression and found that SOCS3 levels were significantly elevated in LPS-treated HPMECs in the sepsis-induced lung injury model group compared to the control group." (PMID 41306613, 2025). "Specifically, following sepsis, F4/80hi macrophages polarize toward an anti-inflammatory phenotype and exhibit elevated expression of anti-inflammatory genes such as Socs3, Il1r2, and Il1rn." (PMID 41465886, 2025). "Examination of SOCS3 protein expression indicated a significant increase in the sepsis group compared to the healthy group." (PMID 39955435, 2025). "Here, we observed that ADAR1 regulates SOCS3 expression by controlling miR-30a maturation, thereby modulating the inflammatory response in the acute stage of sepsis and ameliorating its symptoms." (PMID 32273831, 2020). "SOCS3 plays important role in the course of sepsis and is reportedly involved in the proinflammatory phenotype polarization of the M1 macrophage." (PMID 31093495, 2019). "In sepsis, Siglec-7 acts as a target of suppressor of cytokine signaling 3 (SOCS3) and amplify inflammation through activating monocytes." (PMID 29209331, 2017). "SOCS3 plays an important role in protection against sepsis as it is a negative regulator of LPS-induced inflammation." (PMID 25930108, 2015). "In this way, we identified 38 biomarker genes, including IL6, SOCS3, and IRG1 which were already associated to sepsis by other studies." (PMID 25814982, 2015).
Sepsis (continued). "Futher, PAR1 which induces the expression of SOCS3 in microglia, has been proved to switch from being a detrimental to a benefical receptor during the progression of sepsis in mice." (PMID 22731117, 2012). "The up-regulation of TNF-α, IL-1α, IL-1β, CXCL-10, SOCS3, IL-10 at 1 and 2 h in the present study was similar to that observed in blood profiles of sepsis patients at early stages." (PMID 23009705, 2012). "We found greater SOCS-3 expression with PN compared with EN in sepsis, whereas in sham-operated animals the SOCS-3 expression was lowest in those given PN." (PMID 17634149, 2007). "This further supports the hypothesis that SOCS3 may serve as a biomarker of liver injury in human sepsis." (PMID 40808951, 2025). "Finally, we validated the expression of core hub genes (excluding S100A12) in the two mouse models using qRT-PCR, identifying SOCS3 as a potential key biomarker of sepsis-induced liver injury." (PMID 40808951, 2025). "qRT–PCR validation indicated that SOCS3 may serve as a potential biomarker for liver injury in sepsis." (PMID 40808951, 2025). "Through bioinformatics analysis, we identified and validated several hub genes and, for the first time, proposed that SOCS3 may serve as a biomarker for septicemia-induced liver injury." (PMID 40808951, 2025). "Therefore, in this study, we utilized LPS stimulation of only human pulmonary microvascular endothelial cells (HPMECs) to construct a sepsis-induced lung injury model in which a notable increase in SOCS3 expression was observed." (PMID 41306613, 2025). "ADAR1-miR-30a-SOCS3 axis plays a role in reducing inflammation and organ damage in sepsis." (PMID 37635258, 2023). "Additionally, Ezh2 blockage enhances anti-inflammatory Socs3 that inhibits hyperinflammation in sepsis (here and others), multiple sclerosis, and glucose-activated peritoneal fibrosis." (PMID 37239864, 2023). "In conclusion, we provided the experimental evidence that lidocaine could alleviate sepsis-induced ALI via activating AMPK/SOCS3 axis to inhibit the ASK1-p38-TF/MMP-2/9 signaling pathway." (PMID 34804364, 2021). "For example, IL1R2 and SOCS3 were reported to drive the neonatal innate immune response to sepsis." (PMID 32908583, 2020). "The qPCR results suggest that GK and PFKFB3 might contribute to the progression of S. aureus-induced sepsis, and CEACAM1, TNFAIP6, PSTPIP2, SOCS3, and IL18RAP might be closely linked with E. coli-induced sepsis." (PMID 31093495, 2019). "The qPCR results suggested that GK and PFKFB3 might contribute to the progression of S. aureus-induced sepsis, and GK, CEACAM1, TNFAIP6, PSTPIP2, SOCS3, and IL18RAP might be closely linked with E. coli-induced sepsis." (PMID 31093495, 2019). "SOCS3 in the spleen, lung, and peritoneal leukocytes is up-regulated during sepsis." (PMID 29209331, 2017). "Therefore, kallistatin most likely modulates TLR signaling and expression through induction of SOCS3 synthesis, leading to protection against sepsis-induced inflammatory response and organ injury." (PMID 25930108, 2015). "Additionally, we analyzed temporal changes in SOCS3 expression during sepsis." (PMID 40808951, 2025). "Additionally, SOCS3 mitigates inflammatory damage by promoting macrophage polarization to the M2 phenotype, maintaining vascular homeostasis, and improving survival rates in sepsis patients." (PMID 40808951, 2025). "Similarly, in sepsis-induced cardiomyopathy, SOCS3 may participate in pathological processes by regulating cardiomyocyte growth, apoptosis and immune response modulation." (PMID 41306613, 2025). "We observed that ADAR1 significantly increased the expression of suppressor of cytokine signaling 3 (SOCS3) in macrophages and reduced the expression of interleukin-6 in macrophages and the serum, thereby reducing intestinal permeability and mucosal injury in mice with sepsis." (PMID 32273831, 2020). "SOCS-3 may be of particular importance in the mechanism of GH resistance in sepsis." (PMID 17634149, 2007).
Sepsis (continued). "In sepsis-induced ARDS, dysregulated inflammation is a major contributor to lung injury and hypoxemia, with SOCS3 potentially influencing the occurrence and progression of ARDS by modulating inflammatory signaling pathways." (PMID 41306613, 2025). "For example, while our study highlights the significant role of the SOCS3 gene in both ARDS and SIC—a gene that has been relatively understudied in the literature—this underscores the complexity of sepsis and its complications." (PMID 41306613, 2025). "An immune cell-specific study has found that MMP9, ARG1, CXCL3, SOCS3, CCR7, and IL-10 are differentially expressed in T cells and monocytes from sepsis patients compared with healthy individuals." (PMID 35721566, 2022). "While IL6 was previously identified as biomarker for sepsis, GADD45B, SOCS3, and IRG1 were shown to be up-regulated in septic patients." (PMID 25814982, 2015). "CIS was increased in sepsis by EN and SOCS-2 in sham operation by PN, whereas SOCS-3 was increased with PN after CLP and decreased with PN after sham operation." (PMID 17634149, 2007). "The role of SOCS3 in inflammation and immune regulation may be critical for ARDS and myocardial disease induced by sepsis." (PMID 41306613, 2025). "In addition, SOCS3, a suppressor of the JAK2/STAT3 pathway, exhibited higher expression in the sepsis and TCZ16 groups, as anticipated, in response to high inflammation." (PMID 39955435, 2025). "Similarly, monocytes from sepsis plus ARDS patients in comparison to sepsis-only patients revealed a gene signature enriched for IFN-stimulated genes and downregulation of immunomodulation genes, such as SOCS3 (suppressor of cytokine signaling 3)." (PMID 36829255, 2023). "As SOCS3 can inhibit the IL-6/STAT3 pathway, ADAR1 is expected to reduce IL-6 levels by regulating the expression of SOCS3, thereby inhibiting inflammation and alleviating sepsis." (PMID 32273831, 2020). "Thus, ADAR1 exerts a protective effect against sepsis by reducing inflammation and organ damage via the ADAR1-miR-30a-SOCS3 axis." (PMID 32273831, 2020). "Therefore, kallistatin protects against sepsis-induced inflammation, organ damage and mortality by antagonizing TNF-α- and HMGB1-mediated inflammatory gene expression, and by inducing SOCS3 synthesis." (PMID 25930108, 2015). "• Sepsis and the route of nutrition influence mRNA of SOCS proteins, CIS and SOCS-2, whereas SOCS-3 mRNA is increased in sepsis independent of nutrition." (PMID 17634149, 2007). "SOCS-1 and CIS expression were increased 4 hours following induction of sepsis, but by 24 hours were no different from measurements in sham-operated animals – whereas SOCS-3 expression remained elevated at 24 hours." (PMID 17634149, 2007). "Notably, the analysis identified potential mediators of sepsis-induced immunosuppression, including Arg-1, SOCS-1, and SOCS-3, which were highly upregulated in multiple cell types and negative costimulatory molecules, including PD-1 and CTLA-4 upregulated in sepsis." (PMID 37317092, 2023). "Taken together, these results indicate that lidocaine may promote the expression of SOCS3 in an AMPK-dependent manner, inhibiting the activation of the ASK1-p38-TF/MMP-2/9 signaling pathway to decrease the formation of thrombus and to alleviate sepsis-induced ALI." (PMID 34804364, 2021). "Similar to sepsis-derived MDSCs, the protein level of p-STAT3 also increased gradually while suppressors of cytokine signaling 3 (SOCS3) which was an inhibitor of STAT3 pathway did not change significantly in induced MDSCs." (PMID 38385073, 2024).
type 2 diabetes (30 papers, 2008 to 2024). "Epigenetic associations between SOCS3-cg18181703 and C-reactive protein, inflammatory bowel disease, type-2 diabetes and cognitive abilities also suggest potential pleiotropic effects of SOCS3 gene." (PMID 36303554, 2022). "Of all our replicated CpG associations, only the UACR-associated CpG cg18181703 at SOCS3 showed an association with type 2 diabetes." (PMID 34887417, 2021). "While physical activity increases SOCS3 expression in skeletal muscle, increased SOCS3 expression is induced in the liver, and is linked to the pathogenesis of type 2 diabetes." (PMID 24997069, 2014). "In addition, previous studies have indicated that the SOCS3 methylation level was negatively linked to type 2 diabetes." (PMID 36145200, 2022). "A nested case-control study including 25,372 individuals identified five loci that were associated with future type 2 diabetes incidence, including ABCG1, PHOSPHO1, SOCS3, SREBF1, and TXNIP." (PMID 35399937, 2022). "The authors estimated that 32% of the unexplained risk for future type 2 diabetes among Indian Asians compared with controls was associated with a higher methylation score based on the top five markers at TXNIP, ABCG1, SREBF1, SOCS3 and PHOSPHO1." (PMID 29164275, 2018). "It has been reported that SOCS-3 mRNA levels are increased in the skeletal muscle of type 2 diabetic patients compared with control subjects and correlates with reduced insulin-stimulated glucose uptake." (PMID 18941624, 2008). "The top-ranking pathways enriched in the shared genes include “ECM-receptor interaction” (FRAS1/SPP1, P value = 4.92e-03), “growth hormone synthesis, secretion and action” (ADCY5/SOCS3, P value = 8.84e-03) and “type II diabetes mellitus” (SOCS3, P value = 0.055)." (PMID 35606885, 2022). "MiR-455/SOCS3 pathway may be a potential target for the treatment of abnormal liver lipid metabolism in type 2 diabetes." (PMID 32272865, 2020). "Several of these hits including cg18181703 (SOCS3), cg06126421 (TUBB), and cg05575921 (AHRR) were associated with future incidence of coronary heart disease and smoking, whereas two other CpGs were recently identified in an EWAS of type 2 diabetes." (PMID 31205673, 2019). "SOCS3 is associated with the IL-6–STAT3 pathway in insulin signaling and has been reported to be increased in the skeletal muscle of severely obese or type 2 diabetes patients." (PMID 28706484, 2017). "Indeed, three members of this subnetwork (i.e. MAPK1, INSR, SOCS3) belong to the Type II diabetes mellitus pathway, which fall into the bigger insulin signaling pathway together with SHC1 and ELK1." (PMID 23885764, 2013). "A dysfunctional SOCS3 regulation in myocytes of people with type 2 diabetes is of interest from a broader perspective, as members of the SOCS protein family not only regulate cytokine signaling but also has been shown to inhibit insulin receptor signal transduction." (PMID 22761857, 2012). "From those genes, we manifested that the expression of three critical genes in the type II diabetes pathway was altered, including HK2 (down-regulated), PRKCZ (up-regulated) and SOCS3 (down-regulated)." (PMID 35606885, 2022). "Thus SOCS3 is a potential candidate gene for type 2 diabetes (T2DM)." (PMID 19052638, 2008). "PAK3, CD44, CD5, SOCS3, VAV1, and PIK3CD are negatively correlated with cardiac systolic function, and P2RY1 is positively correlated with LVEF, which may be referred to in studies on type 2 diabetes." (PMID 34925642, 2021).
glioma (28 papers, 2014 to 2025). A benign or malignant brain and spinal cord tumor that arises from glial cells (astrocytes, oligodendrocytes, ependymal cells). "Methylation or silencing of the SOCS3 promoter has been reported to stimulate glioma cell invasion by lowering the expression level of SOCS3 and is also associated with poor clinical outcomes." (PMID 34646310, 2021). "Of these, ten genes (CTSZ, EFEMP2, ITGA5, KDELR2, MDK, MICALL2, MAP 2 K3, PLAUR, SERPINE1 and SOCS3) can potentially classify patients with gliomas into different risk groups." (PMID 32878880, 2020). "We found that SOCS3-deficient bone marrow-derived macrophages display enhanced and prolonged expression of pro-inflammatory M1 cytokines when exposed to glioma tumor cell conditioned medium in vitro." (PMID 26967393, 2016). "Dai' study revealed that high SOCS3 expression is associated with glioma and poor prognosis." (PMID 40838069, 2025). "Furthermore, we showed that the transcription of SOCS1 and SOCS3 is downregulated in IDH1-mutated glioma cases via methylation, suggesting IDHs mutations can regulate protein turnover." (PMID 32931454, 2020). "Also, loss of SOCS3 in macrophages prolonged the survival of glioma-bearing mice." (PMID 37894348, 2023). "Overexpression of β-catenin or SOCS3 promoted glioma stem cell growth, whereas GPM6B overexpression in the context of upregulation of β-catenin or SOCS3 markedly attenuated the promoting effect of β-catenin or SOCS3." (PMID 41450963, 2025). "Cytokines are important coordinators of the microenvironment in which gliomas develop, and thus cytokine regulators such as Suppressor of Cytokine Signaling 3 (SOCS3) play an active role in neural tissue development and cell proliferation." (PMID 38396140, 2024). "SOCS3 is an inhibitor of STAT3 and the error of the SOCS3 regulation program on STAT3 leads to abnormal STAT3 expression in the brain tissue of glioma patients, which is due to phosphorylated STAT3 promoting the expression of many tumorigenesis genes." (PMID 35296090, 2022). "While additional mechanistic studies are necessary, our results suggest that SOCS3 is an important biomarker for glioma and that SOCS3 is related to the proliferation of neuronal tissue." (PMID 34646310, 2021). "Taken together, in the present study, we established an IRRS prognostic model, composed of VEGFA, SOCS3, SPP1, and TGFB2 core DE IRGs, for risk stratification and survival prediction for glioma patients." (PMID 34497663, 2021). "This is consistent with the Pearson correlation analysis, which showed that the expression of SOCS3 and VEGFA has a strong positive association (R-value = 0.69, p < 2.2 × 10−16) in glioma." (PMID 33804433, 2021). "Specifically, most studies showed that SOCS3 is a negative regulator of M1-like polarization in bone-marrow-derived macrophages from mouse and glioma patients, but few studies showed that it is a positive regulator of M1-like polarization." (PMID 34339354, 2021). "Analysis of the Chinese Glioma Genome Atlas Network (CGGA) dataset showed that higher SOCS3, VEGFA, and TEK expression levels are observed in GBM cases with wildtype (WT) IDHs." (PMID 33804433, 2021). "In this study, we demonstrated that overexpression of the CRL5 components Elongin B, Elongin C, SOCS3 and Rbx2 predicts poor prognosis of glioma and all GBM subclasses." (PMID 32931454, 2020). "In GBM and glioma cases carrying IDH1 mutations, SOCS1 and SOCS3 methylation was increased and their expression was downregulated." (PMID 32931454, 2020). "A higher-than-median expression level of SOCS1, SOCS3 or TCEB1 also predicts a poor prognosis for WHO grade-IV glioma patients compared to those with lower-than-median expression." (PMID 32931454, 2020). "Patients with primary glioma, WHO grade IV glioma, and recurrent glioma in whom SOCS3 expression levels were higher than the median consistently demonstrated unfavorable OS rates compared with those with lower-than-median SOCS3 expression levels." (PMID 32931454, 2020).